RGPD8 (RANBP2 like and GRIP domain containing 8)
Synonyms: RANBP2ALPHA; RANBP2L1; RGP8
Tractability: PROTAC: ubiquitination databases record sites on it.
Gene: Protein-coding gene on chromosome 2 (112,368,369 to 112,434,488, reverse strand). Ensembl gene ENSG00000169629.
Subcellular location (Human Protein Atlas): Nuclear membrane; Vesicles
Gene Ontology:
Molecular function: small GTPase binding; SUMO transferase activity
Biological process: NLS-bearing protein import into nucleus; nuclear export
Cellular component: nuclear pore; Golgi apparatus
Genetic constraint (gnomAD): Loss-of-function variants: 12 observed, 46.78 expected, observed/expected ratio (o/e) 0.26, 90% interval 0.16 to 0.42. The synonymous counts are far from expectation, so gnomAD's model fits this gene poorly and the ratio says little. Missense variants: 155 observed, 520.17 expected, observed/expected ratio (o/e) 0.3, 90% interval 0.26 to 0.34. Synonymous variants: 57 observed, 183.27 expected, observed/expected ratio (o/e) 0.31, 90% interval 0.25 to 0.39.
Homologues: Orthologues: zebrafish ranbp3a (5% identical), Drosophila melanogaster RanBP3 (5% identical). Paralogues in human: RGPD5 (99% identical), RGPD6 (99% identical), RGPD3 (95% identical), RGPD4 (94% identical), RGPD1 (93% identical), RGPD2 (93% identical), RANBP2 (84% identical), RANBP3 (7% identical), RANBP3L (4% identical), RANBP1 (4% identical).
Diseases named in the same sentence as RGPD8 in open-access papers:
RGPD8 is named in the same sentence as 2 diseases in open-access papers, as found by Europe PMC text mining. Sharing a sentence is not in itself a finding about the gene and the disease. The quoted sentences say what the papers report.
cancer (3 papers, 2020 to 2025). A tumor composed of atypical neoplastic, often pleomorphic cells that invade other tissues. "For CSS, patients with cancer-specific death presented higher expression patterns of RGPD8, BAIAP2L1, and DDX11 and lower expression patterns of SLC16A9, FRAS1, AQP1, TMEM38B, and PRUNE2, in both the univariate and multivariate analyses." (PMID 31963294, 2020). "Additionally, there were DMRs overlapping with the gene bodies of METAP1D, RGPD8, and PKP3, which have been shown to be up-regulated in LUAD and promote cancer growth, and whose methylation status has been linked to in utero nicotine exposure." (PMID 37742993, 2023). "Upregulation of RGPD6, RGPD5, RGPD8, RGPD2, NUP210L, and PLCL1 has been observed in invasive tumors, implicating this functional network in the remodeling of ECM stiffness and integrin signaling, both of which enhance cancer cell migration." (PMID 40370715, 2025). "Moreover, the expression levels of 13 out of 16 genes (except RGPD8, NPR3, and KDM5C) differed according to the cancer stage." (PMID 31963294, 2020).
RGPD8 also shares sentences with these, for which no sentence is quoted: Crohn disease (1 paper).